CD4 (CD4 molecule)
Diseases named in the same sentence as CD4 in open-access papers (continued):
Sharing a sentence is not in itself a finding about the gene and the disease.
tumor (continued). "CD4+ T cells play an important role in antitumor immunity by regulating antigen‐specific immune response, thereby coordinating the complex antitumor immune process of inhibiting tumor progression and development." (PMID 37792639, 2023). "Additionally, CD4+ T cells have the ability to induce tumor rejection via the major histocompatibility complex class II (MHC II)-dependent pathway as well as regulation by Tregs." (PMID 38067231, 2023). "Recent studies have shown that polyamine blocking therapy (PBT) reduced not only CD206+F4/80+ M2 macrophages but also tumor infiltrating cells including Gr-1+CD11b+ myeloid-derived suppressor cells (MDSCs) and CD4+CD25+ Tregs and concomitantly increased granzyme B+ and IFN-γ+ CD8+ T cells in TME." (PMID 37653021, 2023). "Besides, CD4+ T cells can secret multiple cytokines to mediate anti-tumor effects, for instance, the secretion of IL-2 from Th1 cells is essential for the function of CD8+ T cells such as the initiation of the immune response and its growth." (PMID 37287989, 2023). "CD4+ helper T (Th) cells are key modulators of tumor immunity." (PMID 37077908, 2023). "The immunomodulatory properties of SCFA may be the key factor in altering the amount of immune-suppressing Tregs and tumor-killing CD4+ and CD8+ T cells." (PMID 37432206, 2023). "However, TRAIL−/− mice displayed significantly decreased pancreatic cancer tumor volumes, and this tumor suppression was due to the reduction in regulatory CD4+ cells within the tumor." (PMID 37605148, 2023). "However, this paradigm was recently challenged since cDC1s can also induce naïve CD4+ T-cell priming by presenting tumor antigens via the MHC II pathway." (PMID 36949244, 2023). "In IPSLow tumors, CD8+ and CD4+ T cells are abundantly recruited in the tumor parenchyma." (PMID 36998102, 2023). "Our exploratory analysis of RNA sequencing from baseline tumor samples revealed a significant association between immune hot tumors (those infiltrated with myeloid dendritic cells, CD8+ T cells, or regulatory CD4+ T cells) and development of an irAE, even after accounting for histologic subtype." (PMID 37787759, 2023). "A recent study has discovered that CD4+ T cells could control tumor growth and progression by secreting th1 cytokines to reactivate tumor cell senescence." (PMID 37325889, 2023). "For example, CD4 T cells can employ several mechanisms to participate in tumor attack." (PMID 37810959, 2023). "This reporter mouse model may be a useful tool to researchers performing tumor immunotherapy studies where visualization of CD3+ immune cells (such as CD4 T, CD8 T, or NKT cells) via mCherry-expression is beneficial." (PMID 37020875, 2023). "In contrast, in combination with α-PD-L1 (75 mg/mouse), the immunotherapeutic impact of Fe-TBP was significantly enhanced, inducing more than 90% tumor regression in local and distant tumors and increasing tumor-specific T cells such as infiltrating CD4+ and CD8+ T cells." (PMID 36987269, 2023). "Our experiments mimicking the condition of tumor initiation when only a low number of breast CSCs are present in comparison to the infiltrating effector CD4+T cells, revealed that CSCs convert CD4+CD25− T cells into immunosuppressive CD4+CD25+FOXP3+ Treg cells in a contact-independent manner." (PMID 38038865, 2023). "These cytotoxic cells express Eomes and GzmK together with uniquely high expression of the signaling lymphocytic activation molecule family member 7 (SLAMF7), a surface protein that was already described to characterize CD4+ T cells with cytotoxic potential in tumor and autoimmune diseases." (PMID 37965314, 2023). "However, it has been shown in mice that low-affinity CD8+ T cells are capable of generating an anti-tumor response only in the presence of CD4+ T cells." (PMID 37600765, 2023). "These experiments might include multiplex immunohistochemistry studies (e.g., staining with anti-CD3, anti-CD8, and anti-CD4 monoclonal antibodies) of the tumor tissue itself." (PMID 36992227, 2023).
tumor (continued). "To investigate the correlation between NI subgroups and tumor immunity, we investigated the abundance of immune cells’ infiltration in NI subgroups and found that activated B cells, activated CD4 T cells, and activated CD8 T cells were significantly higher in NI subgroups I than in NI subgroups II." (PMID 37351504, 2023). "In addition to priming, CD4+ T cells can pair with other immune cells such as macrophages, eosinophils, and natural killer cells to mediate tumour clearance." (PMID 37628721, 2023). "Furthermore, local intra-tumoural administration of ICI-OVs elicited pronounced systemic increases in activated CD4+ and CD8+ T cells, increased effector memory and central memory T cells and decreased MDSC and Treg populations." (PMID 37627206, 2023). "Specially, PD-L1 expression on platelets could not only reflect that on tumor, but also inhibit CD4+ and CD8+ T cells, which provided a new perspective to overcome the limitations of traditional quantification of PD-L1 expression on tumor cells." (PMID 36845142, 2023). "Next, we sought to determine whether the F12 E6-specific CD4+ TILs were capable of direct tumor cytotoxicity." (PMID 36512410, 2023). "The cross-G function—a form of probabilistic nearest neighbour analysis—was used to demonstrate shorter OS for patients with CD4+ forkhead box P3-positive (FoxP3+) Treg cells and tumour cells in close proximity (hazard ratio (HR) 1.52, 95% confidence interval [95%CI] 1.11–2.07 and p = 0.009)." (PMID 37835491, 2023). "In addition, PD-L1 is mainly overexpressed on tumor cells, but this study found that the expression of PD-L1 on CD4+ T cells from peripheral blood in cHL patients was up-regulated." (PMID 37933048, 2023). "Correlation of immunoscores with CIBERSORT analysis showed abundance of the majority of the 22 tumor-infiltrating immune cells in “immune hot” tumors with M2-type macrophages, CD4 memory resting T-cells, and resting mast cells being the most identified cells in the TIME." (PMID 37337080, 2023). "Combining T cell transfer with anti-CTLA-4 treatment enhanced the anti-tumor activity of CD4+ CTL." (PMID 37965314, 2023). "Although CD4+ T cells were dispensable for tumor lysis, we showed that CD4+ T cells influence NK cell activation and vice versa which may be important in vivo." (PMID 37923822, 2023). "Together with the high levels of HER2-reactive serum IgG levels, our data suggest that VSVΔ51+T-DM1 treatment elicits a humoral response centered on CD4+ T-cell tumour infiltration and activation, systemic dendritic cell activation by VSVΔ51 or T-DM1, followed by anti-tumour IgG production." (PMID 37153626, 2023). "CD4+FoxP3+ Tregs were associated with a bad prognosis in the TME (P = 0.044), as well as CD4+FoxP3+ Tregs surrounding S15− tumor cells (P = 0.035), and S15+ tumor cells (P = 0.008)." (PMID 37674198, 2023). "And vitamin C induced a major increase in IFN-γ-producing CD4+ cells in the tumor tissues." (PMID 37283769, 2023). "When this occurs, the PDAC TME has a high content of regulatory T cells (Tregs), tumour associated macrophages (TAMs), and myeloid-derived suppressor cells (MDSCs), as well as a relatively low prevalence of anti-tumour CD4+ and CD8+ T cells, natural kill (NK cells), and dendritic cells (DCs)." (PMID 37190281, 2023). "CD4 resting memory T cells, resting mast cells, and resting DCs may also contribute to tumor progression to the progressive stage." (PMID 36935487, 2023). "Interestingly, the ratio of TNFα+ CD4+ to IL-17A+ CD4+ T cells was also skewed towards more IL-17A+ CD4+ T cells in the tumor tissues versus STM while the ratios of IFNγ+ CD4+ and TNF+ CD4+ T cells showed a small change towards more TNFα." (PMID 38074634, 2023). "Therefore, this study aims to preliminarily explore the correlation between the radiomics features of DCE-MRI and the infiltration degree of CD8+ and CD4+ tumor-infiltrating T lymphocytes and lay the foundation for future research." (PMID 37342362, 2023).
tumor (continued). "Studies have shown that dentritic cell and CD4+T cell are involved in tumor progression." (PMID 37064114, 2023). "While the spleen composition in both experimental groups remained unchanged (data not shown), the immune infiltrate of FIH-KO tumors was characterized by an increase in terms of percentage and absolute numbers of tumor-infiltrating lymphocytes (CD4+, CD8+, and NKs) compared with WT tumors." (PMID 37707961, 2023). "Notably, mice treated with the RARγ agonist IRX4647 and an anti-PD-L1 agent statistically-significantly elevated CD4+ T helper cells in the spleen and tumor." (PMID 37689790, 2023). "Furthermore, Trabid depletion in tumors increased the frequencies of tumor-infiltrating CD4+ T cells and CD8+ T cells but decreased that of Treg cells." (PMID 37237031, 2023). "Decreases in the quantity of CD4 + tumor infiltrating T cells (TIL) have been described for advanced-stage HCC suggesting a reduction could indicate tumor progression." (PMID 37247078, 2023). "Given the increase in Gr-MDSCs, we hypothesized that they might mediate residual immune suppression, preventing a complete tumor-inhibitory CD8+ T cell response in our Cd4;Tcf7fl/fl mice." (PMID 36239683, 2023). "Conversely, a decrease in the CD4+/CD8+ ratio may be associated with a restricted immune response, allowing the tumor to proliferate." (PMID 37206348, 2023). "Nevertheless, downregulation of CD4 in the TME could be a long-lasting effect induced by tumor cells to promote tumor progression." (PMID 37266839, 2023). "However, a significant decrease in the percentage of helper (Th; CD4+) and cytotoxic T cells was noticed in the lymph nodes of nsCaEP-treated compared to untreated tumor-bearing (CTRL) mice." (PMID 37630998, 2023). "CD4+T cells are a special type of T cells that can target tumor cells in many ways." (PMID 37274740, 2023). "Furthermore, animals receiving the TSCM-like CD4+ T cells had significantly delayed tumor growth compared to mice receiving the same number of T cells expanded in IL-2." (PMID 37400675, 2023). "The C1-PRF1 cell cluster was highly enriched in tumor-regressing mice, consistent with our hypothesis that CD4 CTLs potently control tumors by direct tumor cell killing." (PMID 37185301, 2023). "FUS has been shown to promote a T-cell-mediated anti-tumor response, characterized by decreased tumor growth and proliferation; increased infiltration of activated, tumor-specific effector CD4+ and CD8+ T-cells; and increased infiltration of inflammatory macrophages." (PMID 37626741, 2023). "Furthermore, abundance of CD4 cells to CD8 cells is higher in the tumor tissue (5.74 vs. 1.65, p = 0.023) as well as the ratio of suppressor cells to pro-inflammatory cells (0.88 vs. 0.34, p = 0.041)." (PMID 37938368, 2023). "Significant differences have not been observed between clinical outcomes according to density in tumor-infiltrating T lymphocytes (TILs) of CD4+/CD8+ lymphocytes, FOXP3+ regulatory T-cells (Tregs), peritumoral and stromal myeloid cells, and PD1-positive and PD-L1-positive immune cells." (PMID 36674951, 2023). "Consistent with the anti-tumor activity observed, we found that the inulin-enriched diet triggered a potent Th1 anti-tumor response, as illustrated by the greater amount of IFNɣ-producing CD4+ and CD8+ TILs." (PMID 36875124, 2023). "However, we found a thin cluster rich in Plasma B cell, Follicular B cell, and Th2-like CD4 + T cell at the interface of tumor parenchyma and neighboring tissues, and this cluster also included plenty lymphoid tissue." (PMID 37164975, 2023). "The extrinsic mechanisms of resistance to immunotherapy largely depend on the different constituents within the TME that interfere with the presence and function of tumor-infiltrating lymphocytes (TILs), including CD4+, CD8+, B lymphocytes, and natural killer cells." (PMID 37111629, 2023).
tumor (continued). "High CD4+CD25+ Treg infiltration has been associated with higher tumor grades, advanced stage, and suboptimal debulking, but not with survival." (PMID 37761986, 2023). "PL restored ROS level (mainly via reversing Duox2/Gpx2), activated oxidative stress/inflammation/immune responses signature genes, reduced cancer cell proliferation/invasion, increased apoptosis and CD3+/CD4+/CD8+ T-lymphocytes in G422TN-tumor on the basis of RT/TMZ regimen." (PMID 37161450, 2023). "Although cytokine production, such as IL-2 and IFN- γ, is a classical model for the function of CD4+ T cells in tumor immunity, the CD40L–CD40 axis that activates DCs through CD4+ T cells and the CD70–CD27 axis that activates CTLs through activated DCs constitute a new concept for helper function." (PMID 37881436, 2023). "A direct impact on helper CD4+ T cells was observed but could have been counteracted by depletion of Treg cells in the circulation and in the tumor." (PMID 36796366, 2023). "We found that α-diversity indices, such as observed_ species, PD_ whole_ Tree, ACE were significantly and positively correlated with counts of immune cells (CD3+, CD4+, CD8+T), indicating that intestinal microorganisms were closely associated with anti-tumor immune effects." (PMID 37201112, 2023). "To further decipher the underlying mechanisms of the protection from tumor recurrence, we analyzed the abundance of naïve T cells (CD62LhighCD44low), TCM (CD62LhighCD44high) and TEM (CD62LlowCD44high) of both CD4+ and CD8+ T cells in the spleen of the mice after re-challenge experiments." (PMID 37296221, 2023). "Moreover, while CD4+ T cells have important roles in tumor control and response to immunotherapy, previous methods have focused primarily on the identification of CD8+ T cell-recognized neoantigens." (PMID 36593398, 2023). "It has been documented that CD4+ T cells can mediate the key to anti‐tumor by secreting cytokines." (PMID 37706625, 2023). "Significant relationships were observed between PD-L1+ tumour cells, CD4+ TILs, and CD8+ TILs." (PMID 37372432, 2023). "However, only depletion of CD8+ T cells increased the tumour volume; by contrast, depletion of CD4+ T cells decreased the tumour volume." (PMID 36470303, 2023). "Several years later, the Rosenberg team reported about a patient with metastatic cholangiocarcinoma who received treatment with ex vivo expanded autologous tumor infiltrating lymphocytes (TILs), containing CD4+ T cells specific for a MHC Class II-restricted mutant tumor antigen (neoantigen)." (PMID 37965314, 2023). "Therefore, activation of cGAS-STING signal can promote the infiltration of CD8+ and CD4+ T cells at the tumor site and the cross-presentation of DCs, thus improving the effect of immunotherapy on tumors." (PMID 37061706, 2023). "T/P-induced senescence in combination with GCV-mediated SMA+ fibroblast depletion led to significantly decreased tumor growth and increased infiltration of NK and CD4+ and CD8+ T cells and their expression of activation (CD69, Sca-1) and cytotoxicity (GZMB) markers compared to T/P treatment alone." (PMID 37142692, 2023). "Tumor antigen-specific CD4+ T effector cells play a crucial role in maintaining anti-tumoral immune responses, producing important cytolytic granule molecules like Gzm and perforin; CD8+ T cells direct toxicity, contributing to protective and pathogenic immunity." (PMID 37892995, 2023). "TGF-β had a complex role in tumor immunity, hampering the ability of T cells to infiltrate tumors, reducing their effector functions, and promoting the differentiation of peripheral CD4+ T cells into Tregs, potentially limiting the host’s natural defense against cancer." (PMID 38139110, 2023). "Interestingly, loss of STING activity appeared to have the greatest effect on CD8+ T cell infiltration into the tumor relative to CD4+ T cells or Tregs." (PMID 36394642, 2023).
tumor (continued). "As expected, FOXP3 predominantly activated in Treg and CD4+ Tex, and within each tumor, whether for PT or BM, the percentage of them showed significant correlation (Pearson correlation, R = 0.45, p = 0.005)." (PMID 36671569, 2023). "Furthermore, T‐bet can improve the antitumor effect of CD4+ CAR‐T cells against B7H6‐expressing tumor cells by upregulating the secretion of cytokines and cytotoxicity." (PMID 37829505, 2023). "Further analysis showed that AGER DNA methylation may be correlated with tumor-infiltrating lymphocytes, especially CD4+ T cells, active CD8+ T cells, memory B cells, natural killer T cells, and type 2 T helper cells." (PMID 37497166, 2023). "The immune cell component of the TME is formed by tumor-infiltrating lymphocytes (TILs, including CD4+ and CD8+ T cells, B cells, natural killer T cells, and myeloid lineage cells (macrophages, neutrophils, monocytes, eosinophils, myeloid-derived suppressor cells or MDSCs, and mast cells or MCs))." (PMID 37370836, 2023). "Besides, in other diseases such as tumor, as an infinitely proliferating cell, it requires a large amount of Gln uptake and decomposition, as do anti-tumor CD4+ T cells such as Th1 and Th17 cells." (PMID 37545506, 2023). "Furthermore, tumor-infiltrating B cells produce cytokines that stimulate the formation of tertiary lymphoid structures, which facilitate the formation of CD4 memory T cells and proliferation of activated CD8+ T cells through CD27–CD70 interactions." (PMID 36765877, 2023). "These increased tumor-infiltrating lymphocytes include CD4+ T cells, Foxp3+ Treg cells." (PMID 37143538, 2023). "Taken together, the data suggest combined immunotherapy and Trp2Vax treatment increased frequency and effector functions of tumor-infiltrating effector cells (CD4+ and CD8+ T cells an NK cells), and potentially activate APCs such as macrophages for antigen presentation." (PMID 36911698, 2023). "CD8 + T, CD4 + T, and NK cell infiltration levels in tumor tissue prior to nCRT were 3.5% ± 3.6%, 1.4% ± 1.6 and 1.6% ± 1.6%, respectively; after nCRT, these values were increased to 5.6% ± 6.1%, 3.5% ± 3.0 and 4.5% ± 2.6%, respectively (p < 0.001, p = 0.164 and p = 0.022)." (PMID 35794399, 2023). "Moreover, most of these CD4+ T cells were FOXP3+ regulatory T cells that were being recruited by the tumor cells via chemokines such as CCL17 and CCL22." (PMID 36768631, 2023). "Similarly, knocking down galectin-1 expression in 4T1 cells led to a diminished proportion of CD4+CD25+Foxp3+ Treg cells within the tumor microenvironment as well as peripheral immune organs." (PMID 37047471, 2023). "The ratios of CD8+ T cells and CD4+ T cells in PanCK− stromal cells were negatively correlated with the existence of POSTN+ cells in the tumour regions (R = −.63, P = 3.5e−15; R = −.58, p < .0001), suggesting that POSTN+ CAFs were associated with lower infiltration of T cells in NSCLC." (PMID 38115703, 2023). "Vaccination against the most common H3K27 alteration, H3 K27M, induced mutation-specific CD4+ and CD8+ T cell responses in flank tumor models of DIPG, and a phase I clinical trial (NCT02960230) is ongoing to assess safety and efficacy of this vaccine in humans." (PMID 36549282, 2023). "Furthermore, a small population of cytotoxic CD4+ T cells is observed in rejecting tumors and it remains to be determined to what degree this population controls tumor progression." (PMID 37087494, 2023). "Interestingly, we observed an increase in tumor cell killing when CD4 T cells were present, (93% HNSCC cells dead) suggesting that they support ML-NK cell cytotoxicity." (PMID 37865647, 2023). "Overall, these results show that SC144@HABN + anti-PD-L1 combo therapy increased the frequency of tumor-infiltrating CD8+ T-cells and the ratio of M1/M2 macrophages in the TME while decreasing CD4+ Tregs, leading to robust anti-tumor efficacy and establishment of long-term anti-tumor immunity." (PMID 37553327, 2023).